IGF1 (insulin like growth factor 1)
Diseases named in the same sentence as IGF1 in open-access papers (continued):
Sharing a sentence is not in itself a finding about the gene and the disease.
cancer (continued). "In conclusion, lowering the plasma insulin levels or blocking its activity could provide an additional target in cancer therapy in combination with IGF1 inhibition." (PMID 33260481, 2020). "IGF-1 stimulates the proliferation of cancer cells, neoplastic angiogenesis, and metastasis." (PMID 32555993, 2020). "We also provide evidence that circulating concentrations of IGF-1 do not modify the association between height and cancer incidence and mortality." (PMID 32921791, 2020). "Interestingly, people with non-functional GH signaling have very low plasma insulin growth factor 1 (IGF-1) concentrations, are highly resistant to cancer and diabetes type 2 and seem to have a slow cognitive decline." (PMID 33312162, 2020). "In addition, other cancer-drivers/oncogenes, e.g. IGF1, CDK6 and PDK1 that are widely involved in oncogenesis, were also suppressed by TSPX in a CAD-dependent manner." (PMID 30863497, 2019). "In rodents caloric restriction without malnutrition suppressed circulating IGF-1 and insulin levels in proportion to the level of restriction, increased insulin sensitivity and resistance to stress and toxicity, and reduced the cancer risk." (PMID 30774624, 2019). "Thus, insulin and insulin-like growth factor type 1 (IGF-1) signaling pathways represent master regulators of pathophysiological processes directing obesity, DM, and cancer." (PMID 31847392, 2019). "On the other hand, a putative correlation between low IGF1 dosages and cancer risk has not yet been investigated in a systematic fashion." (PMID 31320996, 2019). "Moreover, there is evidence that shows that insulin and insulin-like growth factor-1 (IGF-1) have a functional role in cancer progression and metastasis." (PMID 30987250, 2019). "The “canonical pathway” module was used to analyze the microarray data and to systematically explore the downstream pathways involved in cancer development, such as unfolded protein response signaling, endoplasmic reticulum stress signaling, and insulin-like growth factor-1 signaling." (PMID 29270670, 2018). "MR-409 exerted significant inhibitory effect on IGF-1 expression in all cancer cells tested." (PMID 29983893, 2018). "Importantly, MP subtype cancer cells are more sensitive to inhibition of IGF1/IGF1R pathway than EP subtype." (PMID 29725014, 2018). "In order to determine whether GHRH agonist, MR-409, has an effect on the expression of IGF-1 in cancer cells, 16 human cancer cell lines were examined." (PMID 29983893, 2018). "MK-0646, a humanized IGF-1 mAB, has been previously tested in several cancers." (PMID 29843755, 2018). "We first established that exogenous IGF1 treatment induced the exhibition of cancer stemness, including increased side-population (SP) and ALDH1 activity, accompanied by the increased resistance against the chemotherapeutic agent, 5-FU, and enhanced tumor-initiating ability in vivo." (PMID 30257507, 2018). "Lowering insulin and insulin-like growth factor 1 (IGF-1) levels that stimulate cancer growth could be important features of metformin's mode of action." (PMID 30147674, 2018). "Therefore, IGF-1 can be considered as a well-known cancer inducer and promoter affecting each stage of tumor development, from cellular proliferation to the metastatic phase." (PMID 29721213, 2018). "IGF1 has also been reported to be involved in cancer development." (PMID 30111277, 2018). "The functions of IGF-1 in the development and progression of cancers are also well documented." (PMID 29983893, 2018). "In general, the accumulated evidence indicates that at least in middle-aged subjects, high blood levels of IGF1 (insulin-like growth factor), stimulated by the intake of high-quality proteins, are one of the fundamental physiological factors involved in cancer progression, including melanoma." (PMID 29951370, 2018).
cancer (continued). "Bone resorption releases bone matrix embedded growth factors, such as transforming growth factor beta (TGFβ), insulin-like growth factor 1 (IGF1) and calcium ions, which further fuel cancer cell growth and secretion of PTHLH, thus amplifying and perpetuating the process." (PMID 29988965, 2018). "Biological mechanisms related to this difference can be explained by the fact that high intensity exercise stimulates an acute increase in circulating IGF-1 levels, which contributes to cancer growth because high levels of circulating IGF-1 cannot improve the immune response or weight maintenance." (PMID 29484135, 2018). "Moreover, in this study, we also found that several cancer-related pathways, such as cell cycle, IGF1/mTOR and Fas pathways, were related to three-gene signature." (PMID 29910195, 2018). "In addition, TGF-beta and IGF-1, released from the bone matrix, stimulate the cancer cells to produce additional PTHrP." (PMID 29867053, 2018). "We then tested the effect of recombinant IGF-1 on cancer cell invasion." (PMID 29535813, 2018). "The positive modulation of the let-7 family by SST analogues targets and inhibits the IGF-1/PI3K signaling pathway in addition to maybe inhibiting glucose nutrient in aiding the rapid growth of the cancer cells." (PMID 29973528, 2018). "In castration-resistant prostate cancer, Hsp27 phosphorylation might interact with the IGF-1 signaling pathway and promote cancer progression." (PMID 28903396, 2017). "IGF-1 can stimulate cell proliferation, adhesion, and migration and inhibit apoptosis, which could ultimately result in cancer." (PMID 28949980, 2017). "A relationship between increased levels of circulating insulin and cancer has been investigated, and the results indicated that cancer growth may be affected by IGF-1 signaling axis." (PMID 27903961, 2017). "As the majority of circulating IGF-1 is bound to IGFBP-3, the IGF1:BP3 ratio may play a critical role in cancer progression." (PMID 28417914, 2017). "It is known that increased insulin levels in the body can activate IGF-1 signaling which might furthermore promote the cancer cell proliferation." (PMID 28977962, 2017). "Although IGF-1 functions as an epithelial cell mitogen and has been in implicated in cancer development, increased IGF-1 levels have not been associated with tumour malignancy in some models." (PMID 28143425, 2017). "Despite mechanistic implications for IGF-1 bioavailability, population-based studies have failed to capture a consensus on the impact of IGFBPs on cancer risk and outcomes." (PMID 28959684, 2017). "As these techniques focus on breathing, emotional awareness, and cognitive moment-by-moment awareness, increased IGF-1 levels may therefore be related to the enhancement of cognitive function, and to cancer prevention." (PMID 28231775, 2017). "There is some concern about the possible association between elevated IGF1 and cancer; however, causality between elevated IGF1 and cancer has never been established." (PMID 28566441, 2017). "Specifically, five cancer types shared a change in AGTR1 and IGF1 genes, which implies that there may be similar underlying disease mechanisms among these cancers." (PMID 28178311, 2017). "Xenograft model was used to study the IGF-1 function in cancer development." (PMID 29255466, 2017). "IGF-1 is a growth factor involved in cancer proliferation and inhibition of apoptosis." (PMID 28410237, 2017). "Thus, we observed that the AGTR1 (GPCR protein) and IGF1 genes were shared by 5 different cancer types, which are shown in red." (PMID 28178311, 2017). "Both semi-quantitative and quantitative PCR analysis demonstrated that Epidermal Growth Factor (EGF), Fibroblast Growth Factor (FGF), and Insulin-like Growth Factor (IGF-1) (factors known to support growth of cancer cells) were expressed by both primary tumor and brain metastasis CAFs." (PMID 28649646, 2017).
cancer (continued). "Amplified IGF1 signaling has been shown to promote the development and progression of cancer, and furthermore, IGF1 has been identified as an important lymphangiogenic factor in several cancer types." (PMID 28624797, 2017). "In addition, there are many other factors that can stimulate cancer cells to generate ROS, such as insulin-like growth factor I (IGF1), and fibroblast growth factor-2 (FGF2)." (PMID 28282928, 2017). "Hence, we concentrated on the main mechanisms proposed for the anti-aging effects of CR: modulated insulin/IGF-1, mTOR, NF-ĸB and Sirtuin signaling, reduced oxidative stress, the disposable soma theory, anti-cancer mechanisms and increased autophagy." (PMID 28768896, 2017). "Studies by re-expression of klotho in cancer cells revealed that sKl acts as a tumor suppressor by inhibiting multiple signaling pathways that include the insulin/IGF-1 pathway, FGF pathway, Wnt signaling pathway, and transforming growth factor-β1 (TGF-β1) pathway." (PMID 29250031, 2017). "IGFBP-2 has been demonstrated to be an enhancer of IGF-1 function in several types of cancer." (PMID 28903396, 2017). "Overall, Akt/PKB is one of the most frequently activated kinases in human cancer, and ectopic expression of a dominant-negative kinase-dead variant inhibited the ability of IGF1 to prevent apoptosis in Saos-2 cells." (PMID 28316059, 2017). "In addition, expression of signaling factors downstream of IGF-1 has been correlated with either resistance or sensitivity to several cancer therapies." (PMID 28539118, 2017). "Hyperglycemic conditions also increase proliferation rate of several cancer cells, and this effect may be amplified when in combination with high insulin or IGF1 levels." (PMID 28880250, 2017). "A better understanding of the effects induced by IGF1 through GPER at the crossroad between cancer, endothelial and stromal cells, may pave the way for the therapeutic manipulation of the multiple signaling networks that control tumor angiogenesis." (PMID 29212519, 2017). "A lower serum level of IGF-1 was related to a more advanced cancer stage (P < .01)." (PMID 28107416, 2017). "IGF-1, a well-known pathway with an affinity for insulin, is also critical to cell proliferation and apoptosis and has been shown to be related to various types of cancers." (PMID 29228629, 2017). "These approaches may be useful options in the ambition to exploit the full repertoire of insulin/IGF-1 modulation against cancer." (PMID 26878387, 2016). "In addition, IGF1 system dysregulation has been reported in cancers such as NSCLC and in other tumors." (PMID 27213344, 2016). "Insulin-like growth factor 1 is suggested to play a role in the progression of many cancers, including prostate, colorectal, and breast, as its pro-survival signaling pathways may encourage the proliferation of cancer cells." (PMID 27376028, 2016). "Therefore, to analyze the relative role of IGFBPs and IGF2R in cancer, we developed a mass-action kinetics model of the IGF network that incorporated IGF1, IGF2, IGF1R, IGF2R, and IGFBPs." (PMID 26861122, 2016). "IGF-1 plays a key role in the development and progression of various cancers." (PMID 27764776, 2016). "IGF1/IGF1R signaling was not able to enhance metastasis directly but via inducing tumor‐associated lymphangiogenesis contributing to cancer lymphatic metastasis 32 or via tumor‐associated leukemoid reaction resulting in immunosuppression." (PMID 26923183, 2016). "Lower IGF-1 levels predicted longer survival in both males and females with a history of cancer." (PMID 27077853, 2016). "IGF1 and its binding proteins play key roles in the genesis of many types of cancer." (PMID 27144430, 2016).
cancer (continued). "The sections of BM showed cancer‐associated myelopoiesis in both EphA4‐KO tumor‐bearing mice without or with IGF1 treatment and control WT tumor‐bearing mice." (PMID 26923183, 2016). "The hypothesis about the risk of cancer in GHRT patients was based on the biological nature of growth hormone and insulin-like growth factor-1 (IGF-1)." (PMID 27835910, 2016). "Although inflammation is a powerful driver of tumor growth, it is the aim of this review to focus on the connection between insulin/IGF-1 signaling and cancer, and discuss possibilities to modulate these interactions through DR and pharmaceutical interventions to improve cancer outcomes." (PMID 26878387, 2016). "First of all IGF-1 and insulin share overlapping downstream pathways of cancer cell metabolism." (PMID 27405474, 2016). "The presence of CCL5-Ab or CCR5-pep did not reduce CM-induced expression of IGF-1, suggesting that adipocyte-released factors different from CCL5 may control IGF-1 production by cancer cells." (PMID 27027351, 2016). "IGF-1 was also found to make cancer cells resistant to apoptosis induced by anti-cancer drugs." (PMID 27806706, 2016). "They found that none of the 230 patients with Laron syndrome developed cancer and that only 1 out of 116 patients with inborn IGF-1 loss was diagnosed with malignancy." (PMID 27405474, 2016). "Additionally, increased body weight as well as increased leptin and IGF1 signaling are positively correlated with GI pathologies including inflammatory bowel disease and cancer." (PMID 27558773, 2016). "IGF-1/insulin pathways were show as significant in cancer research." (PMID 27405474, 2016). "By contrast, IGF‐1 that is synthesized locally in an autocrine or paracrine manner may stimulate growth of some cancers." (PMID 27734632, 2016). "They further hypothesize that a lifestyle intervention may reduce IGF-1 levels and thereby potentially cancer penetrance." (PMID 27473440, 2016). "Moreover, bariatric and metabolic surgery are interventions with additional proven insulin-sensitizing effects that reduce the detrimental signaling effects of the insulin/IGF1 axis, thereby exerting a positive impact on the incidence of cancer." (PMID 27612200, 2016). "An important concern with regard to the application of ghrelin receptor agonists in cancer cachexia is that they may increase the levels of growth factors such as GH and IGF-1 to promote tumour growth." (PMID 27852245, 2016). "IGF-1 and insulin share overlapping downstream signaling pathways in normal and cancer cells." (PMID 27405474, 2016). "IGF-1 and insulin share overlapping downstream pathways of cancer cell metabolism." (PMID 27405474, 2016). "In addition, a disorder known as Laron syndrome which is associated with low circulating levels of IGF‐1 and IGFBP‐3 25 are protected from developing cancer, but instead can develop diabetes and cardiovascular disease." (PMID 27734632, 2016). "Regarding IGF1, there is increasing realisation that paracrine (probably macrophage-derived) IGF1 plays at least as important a role as systemic (liver-derived) IGF1 in modulating tissue homeostasis and cancer." (PMID 26284118, 2015). "Restricting the levels of the growth hormone (GH) and the insulin-like growth factor 1 (IGF1), the major mediator of the effects of GH, may also restrict the division rates of stem cells and may reduce cancer risk." (PMID 26682276, 2015). "Different groups have also identified osteopontin, Insulin-like-Growth Factor-1 (IGF-1) or the pro-inflammatory peptide LL-37 as possible secreted factors by cancer cells, which could increase CCL5 levels in MSCs." (PMID 26362269, 2015). "Cross-pathway compensation between insulin and IGF1 signalling has been observed in cancer systems, so that downregulation of multiple pathways, as occurs in ageing brain, may be needed to significantly impair astrocyte survival." (PMID 26297026, 2015). "IGF-1 mutant mouse models live longer and are resistant to cancer." (PMID 26056364, 2015).
cancer (continued). "Additionally, the insulin and IGF-1 levels in cancer patients are proportional to cancer-related mortality." (PMID 25866823, 2015). "Such lesions would be common in all adults, and cancer diagnosis would reflect the probability of these lesions progressing toward a detectable and clinically significant size, with this latter process being influenced by IGF-1 level." (PMID 25866791, 2015). "However, the authors emphasize the need for large-scale population-based studies to further assess the polymorphisms of IGF-1 CA19 and the assessment of cancer risk in a defined population." (PMID 25384883, 2015). "These processes play an important role in cancer progression, indicating that growth of the cancer cells may be stimulated by IGF-1." (PMID 26313144, 2015). "Moreover, a study looking at centenarians’ offspring, found that they had lower circulating IGF-1 bioactivity and a lower incidence of cancer." (PMID 25964779, 2015). "However, there is controversy regarding the pro-mitogenic effects as the mechanisms of insulin/IGF-1 in promotion of cancer development." (PMID 26268733, 2015). "However, all three types of receptor dimers can react with both insulin and IGF1, albeit with variable affinity, making it difficult to establish which ligand plays the main role in cancer." (PMID 26284118, 2015). "Interestingly, the expression of several proteins, such as survivin, aurora kinases, p16(INK4A) and IGF-1, have been found altered in GEP-NENs, and are associated with FOXM1 expression in other cancer entities." (PMID 25797272, 2015). "Vice versa, the CAFs can also secrete similar growth factors, such as hepatocyte growth factor (HGF), keratinocyte growth factor (KGF), and insulin-like growth factors 1 and 2 (IGF-1 and -2), to stimulate the cancer cells to form malignant phenotype such as MICs." (PMID 24587996, 2014). "Our results showed a weaker association for IGF-1 driven cancers than the overall association or non-hormonally driven cancers, suggesting that if the insulin- IGF- 1 axis does play a role it is likely to be as part of a more complex molecular mechanism." (PMID 25526881, 2014). "IGF-1, a well-known pathway with an affinity for insulin, is also critical to cell proliferation and apoptosis and has been shown to be related to various types of cancer, such as breast and colon." (PMID 24927125, 2014). "Insulin-like growth factor 1 dysregulation has been reported in many cancers including NSCLC." (PMID 25628647, 2014). "We subsequently investigated whether the Cyr61 upregulation due to IGF-1 was mediated through the PI3K/Akt pathway which is one of the central pathways in IGF-1 induced cancer growth." (PMID 25062088, 2014). "Indeed, let-7, a well-known tumor suppressor that regulates the multiple components of IGF-1 signaling pathway, is currently targeted as a potential miRNA replacement treatment for cancer." (PMID 25628647, 2014). "Conflicting and often negative results concerning an association between IGF-1 and cancer have been reported for a variety of cancers including HNC." (PMID 25364576, 2014). "However, contrary to IGF-1 levels in other cancers, IGF-1 levels are decreased in HCC and the underlying mechanisms are difficult to explain based on the proliferative effect of IGF-1." (PMID 24586785, 2014). "It is fairly accepted that in the post-developmental stage of life, GH and IGF1 have numerous beneficial actions in skeletal muscle and cardiovascular and nervous systems, but a negative effect on insulin sensitivity and cancer risk." (PMID 24683479, 2014). "In order to further clarify the relationship between GH/IGF-1 and cancer more studies are needed." (PMID 25333772, 2014).